MET (MET proto-oncogene, receptor tyrosine kinase)
Diseases named in the same sentence as MET in open-access papers (continued):
Sharing a sentence is not in itself a finding about the gene and the disease.
gastric cancer (continued). "The dual MET/AXL inhibitor LY2801653 represents a promising therapeutic strategy for the treatment of patients with gastric carcinoma." (PMID 34766112, 2020). "In a panel of MET-amplified gastric carcinoma cell lines, cell growth under anchorage-dependent and independent conditions was studied upon inhibitor treatment or siRNA-mediated knockdown." (PMID 33374770, 2020). "The analysis of 49 gastric cancer cell lines revealed that MET amplification predicts the sensitivity to MET inhibitors." (PMID 31557260, 2019). "Gastric cancers that with positive c-MET expression had higher metabolic tumor volume and total lesion glycolysis compared with c-MET-negative gastric cancers." (PMID 31395059, 2019). "Six MET-amplified gastric cancer cell lines, amongst them Hs746T, were sensitive to both MET antibodies and MET TKIs in cell viability assays." (PMID 31557260, 2019). "Using an in vitro co-culture system, we showed that METhigh/PD-L1high Hs746T (gastric cancer) cells suppressed immune cell function, which was partially recovered by anti-PD-L1 blocking antibody and the clinically administered MET inhibitor crizotinib." (PMID 31480591, 2019). "Until now, no study has investigated the correlation between FDG uptake and c-MET expression in gastric cancer." (PMID 31395059, 2019). "Effects of MET inhibition in advanced gastric cancer were further observed in patient-derived xenograft (PDX) models." (PMID 31557260, 2019). "There were 33 (54.1%) patients with c-MET positive gastric cancers, while the tumors in 28 (45.9%) patients were c-MET negative." (PMID 31395059, 2019). "In the present work, we identified MET amplification as a resistance factor for afatinib therapy in gastric cancer cell line Hs746T." (PMID 31557260, 2019). "To investigate the importance of the receptor tyrosine kinase MET as resistance factor we used the gastric cancer cell line Hs746T, which bears a MET amplification and MET exon 14 skipping due to a splice-site mutation." (PMID 31557260, 2019). "In total, 20% of gastric cancers were either MET-, EGFR- and HER2- positive or MET- and EGFR- or HER2-positive." (PMID 31557260, 2019). "In this study, we investigated the role of MET as a resistance factor for afatinib therapy in the gastric cancer cell line Hs746T by means of MET knockdown." (PMID 31557260, 2019). "Our observation that afatinib resistance in a MET-amplified gastric cancer cell line can be reversed by MET knockdown is in line with data from studies using different entities or anti-HER therapeutics." (PMID 31557260, 2019). "The hepatocyte growth factor receptor (MET) pathway plays an important role in the regulation of growth, survival and invasiveness of gastric cancer." (PMID 31557260, 2019). "In this study, we investigated the prognostic values of semi-quantitative parameters on 18F-FDG PET/CT in patients with advanced gastric cancer according to their expression status of c-MET." (PMID 31395059, 2019). "MET gene amplification is the most frequent genetic alteration that leads to MET activation in non-small cell lung cancer, colorectal and gastric cancers with poor prognosis." (PMID 31040922, 2019). "Treatment targeting c-Met is a promising therapeutic approach for patients with c-MET-amplified gastric cancer." (PMID 31395059, 2019). "In gastric cancer cell lines with high MET amplification (fold>8), 50 nM of PHA665752 were enough to inhibit cell growth." (PMID 31040922, 2019). "In this study, we analyzed the role of MET as a resistance factor for afatinib therapy in a gastric cancer cell line." (PMID 31557260, 2019). "Different antibodies targeting MET or its ligand HGF, and tyrosine kinase inhibitors targeting MET are investigated in clinical trials with gastric cancer patients." (PMID 31557260, 2019).
gastric cancer (continued). "We previously demonstrated that targeting the Golgi apparatus using an Arf1 inhibitor, M-COPA, exerted a selective antitumor effect on gastric cancers amplifying the RTK genes MET and FGFR2 by downregulating the cell surface expression of such RTKs." (PMID 29416720, 2018). "We do also acknowledge that MKN45 cells, one of the gastric cancer cell lines used in this study, have amplified-MET and more likely to dependent on this pathway than ErbB2/HER2 signaling for their survival." (PMID 29686309, 2018). "When compared with control or LV-NC group, the cell growth ratio and free MET level in transfected gastric cancer cells transfected with LV-METase were significantly decreased at 24, 48, and 72 h and showing a time-dependent manner." (PMID 29576621, 2018). "Further, we identified MET amplification as a potential resistance factor to afatinib therapy in gastric cancer cell lines." (PMID 29325228, 2018). "MACC1, a transcriptional regulator of MET, was recognized as an oncogene in gastric cancer (GC); however, its transcriptional or post-translational regulation was not clear." (PMID 29510730, 2018). "Amplification of the MET gene has been found in a number of solid tumor types, including gastric cancer, where sensitivity to a c-Met tyrosine kinase inhibitor was high, and the c-Met pathway was important in maintaining cell survival." (PMID 30134579, 2018). "Induction of sLex on MET by expression of sialyltransferase ST3GAL4 enhances MET signaling and invasion of gastric cancer cells, while ST6GAL1 deficiency causes a reduction of α2,6-sialylation of MET and consequently abolishes motility of HCT116 cells." (PMID 29462882, 2018). "Overexpression of RTKs has been found in a variety of human cancers: EGFR in GBM, lung, esophageal and thyroid cancer; HER2/ErbB2 in lung, bladder, breast and gastric cancer; and MET in lung and gastric cancer." (PMID 29455648, 2018). "Increased HGF intensified malignant phenotype of both MET-unamplified gastric cancer cells and CAFs, then CAFs with intensified malignant phenotype facilitated the expression of HGF, thus building a positive crosstalk." (PMID 30158543, 2018). "A Phase I trial of another c-MET inhibitor SAR125844 enrolled 22 Asian patients with gastric cancer; it showed modest antitumor function in two patients with MET-positive gastric cancer, adverse events were common in these patients." (PMID 30360560, 2018). "In gastric cancer, c-MET expression elevation also is a poor overall survival marker, comparing with c-MET-negative tumors." (PMID 30360560, 2018). "We previously demonstrated that M-COPA effectively downregulated the cell surface expression of MET and showed preferential antitumor efficacy in MET-amplified gastric cancer cells both in vitro and in vivo." (PMID 29416720, 2018). "Intravenous delivery of volitinib in gastric cancer models with amplification of the MET gene showed dose-dependent tumor regression." (PMID 30134579, 2018). "Modulation of O-glycosylation in gastric cancer cells by downregulation of GALNT2 causes increased expression and phosphorylation of MET, which results in increased invasion in vitro and in vivo." (PMID 29462882, 2018). "The present study (NCT01657214) has been completed and aimed to determine the maximum tolerated dose (MTD) and RD of SAR and to explore its antitumor activity in Asian patients with solid tumors, including gastric cancer, and MET amplification." (PMID 29108334, 2017). "Further in the same direction, small cohorts of patients who experience drastic and prolonged disease remission after MET inhibition indicate that at least subgroups of gastric cancers are indeed strongly dependent on MET signaling." (PMID 28532501, 2017). "MET copy number has been assessed in gDNA from gastric cancer and hepatocellular carcinoma cell lines and formalin-fixed, paraffin-embedded tumor samples from patient-derived xenograft models using ddPCR and SNP array or FISH." (PMID 29156716, 2017).
gastric cancer (continued). "In a recent meta-analysis that included data from more than 8000 patients with gastric cancer, IHC-determined MET overexpression was significantly correlated with aggressive tumor behavior." (PMID 29071414, 2017). "Clinical studies with MET-targeting agents have demonstrated a role for MET as a predictive biomarker in patients with gastric cancer." (PMID 29071414, 2017). "MET amplification is reported to occur in approximately 5% of gastric cancer patients, and targeted drug crizotinib is currently undergoing a clinical trial of advanced MET-positive gastric cancer (ClinicalTrials.gov identifier: NCT02435108)." (PMID 28460431, 2017). "We previously demonstrated that activation of MET and mutations in KRAS or CDH1 were linked to the cetuximab insensitivity in gastric cancer cell lines." (PMID 29237412, 2017). "There was also case report about durable complete response of metastatic gastric cancer with anti-MET therapy." (PMID 28052014, 2017). "Aberrant activation of the HGF/c-Met pathway has been observed in various solid tumors, including gastric cancer, most commonly via MET gene amplification." (PMID 29108334, 2017). "The frequency of FGFR2 amplification in gastric cancer (GC) varies from 2 to 9%, with MET and HER2 amplifications being mutually exclusive with FGFR2 amplification." (PMID 28122360, 2017). "Although the frequency of MET amplification in gastric cancer is generally low (2–8.3%), targeting c-Met is a promising therapeutic approach for patients with MET-amplified gastric cancer." (PMID 29108334, 2017). "Advanced pT stages supported MET proto-oncogene activation for deeply infiltrating in gastric cancers." (PMID 28052014, 2017). "In order to know if p45 MET fragment can be generated from WT receptor, mammary epithelial cell line MCF10A and gastric cancer cells GTL16 overexpressing MET were cultured in sparse and confluent conditions and MET expression was analyzed." (PMID 28061464, 2017). "Overall, the data reveal a novel relationship between autophagy and apoptosis in gastric cancer cells exposed to MET inhibitors." (PMID 28881678, 2017). "EGFR, ERBB3/HER3, VEGF, PI3K/mTOR, FGFR2 and MET show promise as new targets for gastric cancer treatment." (PMID 29237412, 2017). "Studies of other c-Met inhibitors in gastric cancer have shown a variety of efficacy outcomes, and differences are probably related to population heterogeneity and the definition of MET gene amplification." (PMID 29108334, 2017). "Pharmacokinetic readout of c-MET in response to c-MET TKI PHA665752 therapy has shown reduced total MET protein in human gastric cancer MKN-45 xenografts due to more necrosis which coincides with lower uptake of c-MET-specific peptide 99MTc-AH-113018." (PMID 28315949, 2017). "For example, previous studies reported that MET pathways activation represented novel drug resistance mechanism of lapatinib unresponsiveness in HER2 positive gastric cancer." (PMID 28052014, 2017). "It has been suggested that c-met amplification and overexpression of MET protein in gastric cancer correlate with poor patient outcomes." (PMID 29071414, 2017). "For ease of clinical translation, we selected the therapeutic antibody-based PET tracer 89Zr-onartuzumab, which has been reported to effectively discriminate c-MET expression in human gastric cancer xenografts." (PMID 28315949, 2017). "This was an open-label, phase I, multicenter, dose-escalation, and dose-expansion trial of SAR125844 in Asian patients with solid tumors, a subgroup of whom had gastric cancer and MET amplification (NCT01657214)." (PMID 29108334, 2017). "In other cell lines, such as MET‐addicted gastric carcinoma MKN45 and EGFR‐addicted CRC SW48 lines, where oncogene inhibition only blocked proliferation, HSP27 knockdown made targeted agents switch from cytostatic to cytotoxic activity." (PMID 28182330, 2017).
gastric cancer (continued). "In vitro cell culture studies showed that miR-449c inhibited gastric carcinoma growth by targeting MET and inhibited NSCLC cell progression by targeting c-Myc." (PMID 27935865, 2017). "In biodistribution studies, uptake in MKN-45 (human gastric carcinoma with high c-MET expression) tumors of 76Br-onartuzumab was about 2-fold higher than in U87-MG tumors (moderate level c-MET expression)." (PMID 28485003, 2017). "The SNU5 gastric cancer cells harboring MET amplification and constitutively activated c-Met signaling was selected for further analysis to compare ABT-700 and antibody 5D5." (PMID 26879245, 2016). "MET amplification was detected by FISH in 2% of patients with gastric cancer; in this case, MET amplification was defined as a MET/CEP7 ratio >2." (PMID 27013592, 2016). "In gastric cancer, MET gene amplification prevalence varies from 2 to 23% among studies limited by small sample sizes." (PMID 27013592, 2016). "INC280 suppressed tumor growth in vivo in a dose-dependent manner, and was extremely well tolerated, especially in mouse xenograft models of MET-driven glioblastoma and gastric cancer." (PMID 27013592, 2016). "Insulin-like growth factor (IGF) pathway activity has been reported in MET-amplified gastric cancer cells and the pathway has been proposed as a means by which HER2-amplified NCI-N87 circumvent lapatinib inhibition." (PMID 27437872, 2016). "miR-34a was shown in vitro to act as a tumor suppressor inhibiting gastric cancer cell proliferation and invasion via downregulation of MET." (PMID 26879132, 2016). "In the MET-amplified Hs746T gastric cancer model, the combination of ABT-700 with docetaxel, an anti-mitotic microtubule inhibitor clinically used for gastric cancer, was more efficacious than either agent given as monotherapy." (PMID 26879245, 2016). "Human cancer cell lines and gastric cancer tissue microarrays were examined for MET amplification by fluorescence in situ hybridization (FISH)." (PMID 26879245, 2016). "IHC staining of GALNT2 and MET was performed in gastric cancer tissues, and IHC scores for GALNT2 and MET staining were correlated using a linear regression model." (PMID 26848976, 2016). "MET overexpression in gastric cancer ranged from 9.6 to 23.8%, as defined by IHC staining intensities of 2+ or 3+, via an SP44 rabbit monoclonal antibody from Ventana Medical System." (PMID 27013592, 2016). "In gastric cancer, MET overexpression or amplification is correlated with tumor stage, metastasis, and shorter overall survival (OS) and progression-free survival (PFS)." (PMID 27013592, 2016). "In gastric cancer, MET activation has been attributed to MET gene amplification or overexpression, which reduces apoptosis and promotes tumor cell survival, proliferation, differentiation and migration." (PMID 27013592, 2016). "In gastric cancer, c-MET expression was reported in 26–74% of cases, and gene amplification in 2–23% of cases." (PMID 27581465, 2016). "GALNT2 downregulation promoted malignant phenotypes in gastric cancer, including cell proliferation, migration, invasion, and tumor metastasis, by increasing MET phosphorylation." (PMID 26848976, 2016). "Anti-tumor efficacy in gastric cancer correlated with MET gene amplification/overexpression and high levels of phosphorylated-MET (p-MET)." (PMID 27013592, 2016). "MET overexpression was detected in vivo in 9.6 to 71% of human gastric carcinomas based on methodology and tissue type." (PMID 27013592, 2016). "An approach to characterization of dual target engagement is also presented for an array of lung and gastric cancer cell lines that reflect diversity in the mutational status of EGFR and c-MET." (PMID 26260789, 2015). "In the case of MET-targeting agents, gastric cancer is a lead indication for the class and provides a good case study of these challenges." (PMID 28536405, 2015).
gastric cancer (continued). "The expression level of the MET protein was significantly decreased in both gastric cancer cell lines (AGS and SGC-7901) after transfection with miR-1 mimics." (PMID 25874496, 2015). "The expression levels of the MET oncogene in gastric cancer tissues were higher than in matched tissues, indicating that overexpression of MET is related to gastric tumorigenesis." (PMID 25874496, 2015). "Intrinsic resistance to MET inhibitors emerges as a major limitation in the application of MET-targeted therapy in gastric cancer." (PMID 26528757, 2015). "The identification of novel miR-1-regulated MET cancer pathways provides new insights into potential molecular mechanisms, target therapy, and prevention of gastric cancer." (PMID 25874496, 2015). "Preclinical studies indicated MET amplification can be used to identify subgroups of patients with gastric cancer who are sensitive to MET inhibitors." (PMID 25965822, 2015). "Preclinically, several cancer progressions, including non-small cell lung cancer, hepatocellular carcinoma, and gastric cancer, have been attenuated by MET inhibition." (PMID 25839163, 2015). "For example, the MET and ALK tyrosine kinase inhibitor crizotinib (PF-02341066) shows differential antitumor effects in non-small cell lung and gastric cancer according to MET and ALK alterations." (PMID 26134786, 2015). "For example, the frequency of MET amplification is rare in gastroesophageal/gastric cancer while MET protein overexpression has been reported in higher incidence." (PMID 26375439, 2015). "The aim of this study is to identify the responsible receptor tyrosine kinases (RTKs) that determine the unresponsiveness of MET inhibitor in MET-positive gastric cancer." (PMID 26528757, 2015). "We measured MET protein expression in the gastric cancer cell lines AGS and SGC-7901 by Western blot." (PMID 25874496, 2015). "Loss-of-function assays using siRNA analysis were performed to examine the effect of MET on gastric cancer cell growth." (PMID 25874496, 2015). "Gastric cancer cells carrying MET amplification and overexpression have been found to be particularly susceptible to its pharmacological inhibition, which corroborates the therapeutic potential of MET inhibition in MET-addicted gastric cancers." (PMID 25473895, 2015). "Previously, we compared the results of an nCounter assay with immunohistochemistry results using three biomarkers (EGFR, HER2 and MET) in a gastric cancer (GC) model." (PMID 26486455, 2015). "We further determined MET expression in the tissue microarray (TMA) which consisted of 75 gastric cancer tissues with 75 matched adjacent non-gastric cancer tissues." (PMID 25874496, 2015). "By using controlled Fab-arm exchange, a set of BsAbs targeting EGFR and c-MET was generated to establish an accurate receptor quantitation of a panel of lung and gastric cancer cell lines expressing heterogeneous levels of EGFR and c-MET." (PMID 26260789, 2015). "Based on the gold standard method of FISH, several studies have reported that MET is amplified in ~5% patients with non-small cell lung cancer and gastric cancer." (PMID 25965822, 2015). "The major target indications for HGF/MET inhibitors are solid tumors, including gastric cancer, NSCLC, HCC, and thyroid cancer." (PMID 28536405, 2015). "Copy number gains of the MET gene are particularly frequent in human gastric carcinoma, where protein overexpression occurs in about one quarter of the cases." (PMID 25473895, 2015). "The present systematic review and meta-analysis suggests that MET overexpression is an indicator of poor prognosis for patients with gastric cancer." (PMID 24416238, 2014). "The combined HRs for 14 studies evaluating MET overexpression on overall survival was 2.57 (95% CI: 1.97–3.35), suggesting that MET overexpression was an indicator of poor prognosis for gastric cancer." (PMID 24416238, 2014).